MIR145 (microRNA 145)
Synonyms: hsa-mir-145; MIR-145; MIRN145; miRNA145
Gene: MicroRNA gene on chromosome 5 (149,430,646 to 149,430,733, forward strand). Ensembl gene ENSG00000276365.
Gene Ontology:
Biological process: miRNA-mediated post-transcriptional gene silencing
Cellular component: RISC complex
Homologues: Orthologues: chimpanzee ptr-mir-145 (100% identical), macaque mml-mir-145 (99% identical), pig ssc-mir-145 (97% identical), dog MIR145 (94% identical), tropical clawed frog xtr-mir-145 (83% identical), guinea pig MIR145 (78% identical), mouse Mir145a (78% identical), zebrafish mir145 (77% identical), rabbit MIR145 (74% identical).
Diseases named in the same sentence as MIR145 in open-access papers:
MIR145 is named in the same sentence as 10 diseases in open-access papers, as found by Europe PMC text mining. Sharing a sentence is not in itself a finding about the gene and the disease. The quoted sentences say what the papers report.
breast carcinoma (4 papers, 2015 to 2021). "We found that Mir145 was significantly downregulated in ATF3-induced mammary tumors, and that its direct targets Klf4 and Sox2 were significantly upregulated." (PMID 33652981, 2021). "As an LA tumor cell suppressor, MIR145 was found to be involved in multiple other types of cancers, including breast cancer, colon cancer, and acute myeloid leukemia." (PMID 32395124, 2020). "Mir145 expression was downregulated ~6-fold in ATF3-induced mammary tumors, consistent with its downregulation in human breast cancers, including basal-like and triple-negative breast cancers." (PMID 33652981, 2021).
male infertility (1 paper, 2018). The inability of the male to effect fertilization of an ovum after a specified period of unprotected intercourse. "MIR143 and MIR145 expression was monitored in FF from an experimental cohort of women pursuing to assisted reproductive technology (ART) with signs of DOR, whereas women pursuing to ART as a consequence of male infertility represented the control group." (PMID 30534420, 2018).
osteosarcoma (1 paper, 2024). A usually aggressive malignant bone-forming mesenchymal neoplasm, predominantly affecting adolescents and young adults. "For example, MIR145 mediates myocardin gene upregulation during muscle differentiation, while the same miRNA induces ROCK1 downregulation in osteosarcoma." (PMID 38413914, 2024).
rhabdomyosarcoma (1 paper, 2020). A rare aggressive malignant mesenchymal neoplasm arising from skeletal muscle. "This approach enabled us to identify several novel and promising rhabdomyosarcoma CSC-specific targets, e.g., ALDH6A1, SOX4, PAX3, CDH15, downregulated MIR145, or phosphorylated RYK, which warrant validation in subsequent mechanistic studies." (PMID 31941033, 2020).
cancer (6 papers, 2018 to 2024). A tumor composed of atypical neoplastic, often pleomorphic cells that invade other tissues. "While DNA methylation-mediated deregulation of MIR145 has been recently described in various cancers, its role in HGSOC remains unexplored." (PMID 39594652, 2024). "These ATF3-induced tumors were also found to have reduced expression of Mir145 and Mir143, leading to upregulation of the transcription factors Klf4 and Sox2 and the cancer stem cell-related gene Kras, respectively." (PMID 33652981, 2021).
tumor (5 papers, 2018 to 2025). "Though less directly linked to inflammation, Mir145 downregulation contributes to an environment permissive of oncogenic and inflammatory signaling, indirectly influencing tumor-associated inflammation." (PMID 40869212, 2025). "Mir145 typically functions as a tumor suppressor in CC, frequently downregulated in tumor tissues." (PMID 40869212, 2025). "Results from the PEA and PPI analysis suggested that PPARG might inhibit the development of LA through the regulation of tumor cell proliferation and transmission-related molecules, including an LA tumor cell suppressor MIR145." (PMID 32395124, 2020).
MIR145 also shares sentences with these, for which no sentence is quoted: acute myeloid leukemia (1 paper); colon cancer (1); colorectal cancer (1); laryngeal squamous cell carcinoma (1).